MTND1P22 (MT-ND1 pseudogene 22)
Gene: Unprocessed pseudogene on chromosome 4 (155,462,873 to 155,463,823, reverse strand). Ensembl gene ENSG00000251407.
Diseases named in the same sentence as MTND1P22 in open-access papers:
MTND1P22 is named in the same sentence as 1 disease in open-access papers, as found by Europe PMC text mining. Sharing a sentence is not in itself a finding about the gene and the disease. The quoted sentences say what the papers report.
COVID-19 (1 paper, 2022). A disease caused by infection with severe acute respiratory syndrome coronavirus 2. "The other locus (index SNP: rs4691707, Pmeta = 6.15 × 10–9 for COVID-19/CAD; Pmeta = 3.03 × 10–10 for COVID-19/HTN) was in the intergenic region closet to the MTND1P22 gene, which may have a role in transcription regulation." (PMID 36187959, 2022).